GCDH (glutaryl-CoA dehydrogenase)
Description:
Catalyzes the oxidative decarboxylation of glutaryl-CoA to crotonyl-CoA and CO(2) in the degradative pathway of L-lysine, L-hydroxylysine, and L-tryptophan metabolism. It uses electron transfer flavoprotein as its electron acceptor. Isoform Short is inactive.
Synonyms: GCD; ACAD5
Tractability: Small molecule: a structure with a bound ligand is known. PROTAC: ubiquitination databases record sites on it; its protein half-life has been measured.
Target class: Enzyme; Oxidoreductase
Gene: Protein-coding gene on chromosome 19 (12,891,128 to 12,915,126, forward strand). Ensembl gene ENSG00000105607.
Subcellular location: Mitochondrion matrix
Subcellular location (Human Protein Atlas): Mitochondria
Pathways (Reactome):
Metabolism: Lysine catabolism
Gene Ontology:
Molecular function: glutaryl-CoA dehydrogenase activity; fatty-acyl-CoA binding; flavin adenine dinucleotide binding; acyl-CoA dehydrogenase activity; oxidoreductase activity, acting on the CH-CH group of donors
Biological process: fatty acid beta-oxidation using acyl-CoA dehydrogenase; L-lysine catabolic process; fatty-acyl-CoA biosynthetic process; acyl-CoA metabolic process; amino acid catabolic process; fatty acid oxidation
Cellular component: mitochondrion; nucleus; mitochondrial matrix
Genetic constraint (gnomAD): Loss-of-function variants: 31 observed, 55.67 expected, observed/expected ratio (o/e) 0.56, 90% interval 0.42 to 0.75. The upper end of that interval is the gene's LOEUF score, 0.75, which puts it in group 3 of 6, group 1 being the genes least tolerant of losing a copy. Missense variants: 509 observed, 625.3 expected, observed/expected ratio (o/e) 0.81, 90% interval 0.76 to 0.88. Synonymous variants: 242 observed, 262.13 expected, observed/expected ratio (o/e) 0.92, 90% interval 0.83 to 1.03.
Gene-disease validity (ClinGen):
ClinGen rates the evidence that GCDH causes each of these diseases.
glutaryl-CoA dehydrogenase deficiency (autosomal recessive): Definitive. Glutaryl-CoA dehydrogenase (GCDH) deficiency (GDD) is an autosomal recessive neurometabolic disorder clinically characterized by encephalopathic crises resulting in striatal injury and a severe dystonic dyskinetic movement disorder.
Homologues: Orthologues: chimpanzee GCDH (99% identical), macaque GCDH (98% identical), pig GCDH (90% identical), rat Gcdh (88% identical), mouse Gcdh (87% identical), rabbit GCDH (86% identical), dog GCDH (86% identical), guinea pig GCDH (77% identical), tropical clawed frog gcdh (73% identical), zebrafish gcdha (73% identical), zebrafish gcdhb (68% identical), Drosophila melanogaster CG9547 (64% identical), and 1 more. Paralogues in human: IVD (29% identical), ACADSB (29% identical), ACADS (28% identical), ACADVL (27% identical), ACAD9 (26% identical), ACADM (25% identical), ACAD8 (24% identical), ACADL (23% identical), ACOX3 (21% identical), ACAD11 (20% identical), ACAD10 (20% identical), ACOXL (17% identical), and 2 more.
Diseases named in the same sentence as GCDH in open-access papers:
GCDH is named in the same sentence as 54 diseases in open-access papers, as found by Europe PMC text mining. Sharing a sentence is not in itself a finding about the gene and the disease. The quoted sentences say what the papers report.
Glutaric aciduria type 1 (57 papers, 2011 to 2026). "Glutaric aciduria type 1 (GA1) is a rare autosomal recessive organic acidaemia caused by deficiency of the glutaryl-CoA dehydrogenase enzyme." (PMID 40025312, 2025). "Glutaric aciduria type 1 (GA1) is caused by pathogenic variants in GCDH, which leads to deficiencies in glutaryl-CoA dehydrogenase (GCDH), an enzyme responsible for the breakdown of lysine, hydroxylysine, and tryptophan." (PMID 40688972, 2025). "Glutaric aciduria type 1 (GA-1) is a significant metabolic disorder caused by genetic deficiency in glutaryl-CoA dehydrogenase." (PMID 39932066, 2025). "Glutaric aciduria Type 1 (GA‐1) is an autosomal recessive inherited disorder caused by GCDH variations." (PMID 39963939, 2025). "Mutations in the GCDH gene cause the neurometabolic disorder glutaric aciduria type 1 (GA1), featuring protein hyperglutarylation, which impairs enzymatic activity and protein interactions to disrupt mitochondrial heterogeneity." (PMID 35428309, 2022). "For example, mutations in GCDH, encoding glutaryl CoA dehydrogenase, are causative for glutaric acidemia type I, wherein large amounts of glutaric acid are excreted in urine." (PMID 35629880, 2022). "For example, one infant (TP022), confirmed as having glutaric acidemia I, was found to have two pathogenic mutations (c.109_110delCA, c.416C>G) in GCDH; however, only one mutation (c.416C>G) was detected with NeoSeq." (PMID 34794485, 2021). "Glutaric acidemia type I (GA1) is a chronic progressive neurodegeneration caused by severe deficiency of glutaryl-CoA dehydrogenase activity, leading to glutaric acid and glutarylcarnitine accumulation." (PMID 34198733, 2021). "Glutaric acidemia type 1 (GA1) is a treatable disorder affecting cerebral organic acid metabolism caused by a defective glutaryl-CoA dehydrogenase (GCDH) gene." (PMID 34344405, 2021). "Glutaric aciduria type 1 (GA1) is an autosomal recessive disorder due to a deficiency of glutaryl-CoA dehydrogenase (GCDH), a mitochondrial matrix protein involved in the catabolism of tryptophan, lysine, and hydroxylysine." (PMID 35096710, 2021). "Glutaric aciduria type 1 is an autosomal recessive disorder caused by mutations in the GCDH gene leading to Glutaryl-coenzyme A dehydrogenase deficiency." (PMID 34925200, 2021). "Genetic defects in the gene that encodes GCDH cause glutaric aciduria type I (GA-I; OMIM #231670), an autosomal recessive neurometabolic disorder of tryptophan, lysine, and hydroxylysine catabolism." (PMID 32992790, 2020). "Glutaric acidemia I (GA-I) is an autosomal recessive metabolic disorder of lysine, hydroxylysine, and tryptophan metabolism caused by a deficiency of the Glutaryl-CoA Dehydrogenase (GCDH) enzyme." (PMID 32508882, 2020). "This is the case for glutaric aciduria type I (GA-I), a rare neurometabolic disorder associated with mutations in the GCDH gene, which encodes for glutaryl-coenzyme A (CoA) dehydrogenase (GCDH)." (PMID 32992790, 2020). "One example is newborn screening for glutaric acidemia type 1 caused by homozygosity for the GCDH, IVS1, G-T, +5 mutation in the Canadian province of Manitoba." (PMID 28222731, 2017). "Glutaric aciduria type I (GA-I) is an inherited metabolic disease caused by deficiency of glutaryl-CoA dehydrogenase (GCDH)." (PMID 28516419, 2017). "Deficiency of glutaryl-CoA dehydrogenase causes type I glutaric acidemia, usually triggered by childhood infection." (PMID 28045121, 2017). "Glutaric aciduria type 1 (GA1) is a rare metabolic disorder of glutaryl-CoA-dehydrogenase enzyme deficiency." (PMID 26219480, 2015). "Glutaric aciduria type I (GA-I) is an inherited metabolic disease due to deficiency of glutaryl-CoA dehydrogenase (GCDH)." (PMID 26693825, 2015). "Glutaric aciduria type I (GA-1) is an autosomal recessive disorder of the degradation of lysine, hydroxylysine, and tryptophan, caused by a defect of the enzyme glutaryl-CoA dehydrogenase." (PMID 24587932, 2014).
Glutaric aciduria type 1 (continued). "Glutaric aciduria type 1 (GA-1) is an autosomal recessive disorder of lysine, hydroxylysine, and tryptophan metabolism caused by deficiency of glutaryl-CoA dehydrogenase." (PMID 24587932, 2014). "Glutaric acidemia type I (GA-I) is a neurometabolic/neurodegenerative disorder caused by deficiency of the mitochondrial enzyme glutaryl-CoA dehydrogenase (GCDH) involved in the catabolism of lysine, hydroxylysine and tryptophan." (PMID 25077029, 2014). "Glutaric aciduria type I (GA I) is an autosomal recessive organic aciduria caused by mutations in the gene encoding glutaryl-CoA dehydrogenase (GCDH)." (PMID 24900967, 2014). "Glutaric aciduria type I (GA-I) is a rare metabolic disorder caused by inherited deficiency of glutaryl-CoA dehydrogenase." (PMID 24135440, 2013). "Glutaric aciduria type I (GA1) is caused by biallelic mutations of glutaryl CoA dehydrogenase." (PMID 37333007, 2023). "Notably, the accumulation of 3-hydroxyglutarate and glutarate in the urine phenocopies the presentation of glutaric aciduria type I, an autosomal recessive disorder caused by a deficiency in glutaryl-CoA dehydrogenase (GCDH), which catalyzes the conversion of glutaryl-CoA to crotonyl-CoA." (PMID 35731870, 2022). "Based on the presented results we conclude that clinical course of glutaric aciduria type 1 in Polish cohort is mild what might suggest some specificity of our population, especially due to the high predominance of the p.Arg402Trp variant in GCDH gene." (PMID 30570710, 2019). "Glutaric aciduria type 1 (GA1) is caused by riboflavin-dependent glutaryl-CoA dehydrogenase (GCDH) deficiency, encoded by the GCDH gene (localized on chromosome 19p13.2)." (PMID 30570710, 2019). "Glutaric aciduria type 1 (GA1) is an autosomal recessive metabolic disorder caused by deficiency of glutaryl-CoA dehydrogenase enzyme encoded by the GCDH gene." (PMID 27672653, 2016). "Glutaric aciduria type 1 (GA1) is an inherited neurometabolic disorder caused by mutations in the GCDH gene encoding glutaryl-CoA dehydrogenase (GCDH), which forms homo- and heteromeric complexes in the mitochondrial matrix." (PMID 24498361, 2014). "Glutaric aciduria type 1 (GA1) is an autosomal recessive inherited neurodegenerative disease caused by a deficiency in the activity of glutaryl-CoA dehydrogenase (GCDH)." (PMID 23658800, 2013). "Mutations in the GCDH, an enzyme localized just downstream of the SacPath, lead to GA1 disease, also known as Glutaric Aciduria type I." (PMID 41194801, 2025). "Another genetic disease, glutaric aciduria type I (GA1), localizes just downstream of the SacPath and is caused by mutations abolishing the enzymatic activity of glutaryl-CoA dehydrogenase (GCDH)." (PMID 41194801, 2025). "Glutaric aciduria type I (OMIM #231670), a rare metabolic disorder caused by mutations in the GCDH gene, was first described in 1975." (PMID 41462359, 2025). "The genetic dystonias were associated with the following genes: TOR1A, THAP1, SGCE, KMT2B, HPRT1 (Lesch Nyhan disease), PANK2 and GCDH (Glutaric Aciduria type 1)." (PMID 36445406, 2023). "Glutaric aciduria type 1 (GA1, OMIM#231670) is a rare, autosomal recessive inborn error of metabolism caused by a deficiency of glutaryl-CoA dehydrogenase (GCDH)." (PMID 27246831, 2016). "Glutaric aciduria type I (GA-I; MIM #231670) is an autosomal recessive disorder caused by mutations in the mitochondrial enzyme glutaryl-CoA dehydrogenase (GCDH; EC 1.3.99.7; MIM *608801)." (PMID 23326493, 2013). "In glutaric aciduria type 1 (GA1), glutaryl-CoA dehydrogenase (GCDH) deficiency has been shown to be responsible for the accumulation of glutaric acid and striatal degeneration." (PMID 23658800, 2013).
Glutaric aciduria type 1 (continued). "MALDI-MSI and MALDI-IRIS were used to study two related IMDs inthe l-lysine catabolism pathway: pyridoxine-dependent epilepsy(PDE-ALDH7A1) and glutaric aciduria type 1 (GA1).These disorders are caused by mutations in ALDH7A1 and GCDH, which encode the enzymes antiquitin and GCDH, respectively." (PMID 40521743, 2025). "Mixed movement disorder, including chronic chorea, may also be present in glutaric aciduria type 1 (GA1), an autosomal recessive condition caused by pathogenic variants of the glutaryl CoA dehydrogenase (GCDH) gene." (PMID 38921008, 2024). "Glutaric acidemia type I (GA I) (OMIM 231670) is an autosomal recessive disorder caused by mutations in the gene GCDH, located on the short arm of the chromosome 19, leading to deficient activity of the mitochondrial enzyme glutaryl-CoA dehydrogenase (GCDH)." (PMID 34955754, 2021). "Glutaric acidemia type I (GA1, OMIM 231670) is an autosomal recessive neurometabolic disorder caused by biallelic pathogenic variants in GCDH resulting in deficiency of glutaryl‐CoA dehydrogenase (GCDH)." (PMID 34258142, 2021). "Glutaric aciduria type I (GAI, OMIM #231670) is caused by the deficiency of the mitochondrial enzyme glutaryl-CoA dehydrogenase (GCDH), responsible for the oxidative decarboxylation of glutaryl-CoA to crotonyl-CoA, in the catabolic pathways of lysine and tryptophan." (PMID 29743968, 2018). "Glutaric aciduria type 1 (GA1; OMIM #231670) is a rare neurometabolic disorder of lysine, hydroxylysine, and tryptophan metabolism caused by biallelic pathogenic variants in the GCDH gene, encoding the mitochondrial matrix protein glutaryl‐CoA dehydrogenase (GCDH, EC 1.3.8.6)." (PMID 41485880, 2026). "For example a clinical picture of significant dystonia, macrocephaly and MRI revealing widened Sylvian fissures and basal ganglia abnormalities may be confirmed as glutaric aciduria type 1 with urine organic acid analysis and genetic study of the glutaryl CoA dehydrogenase (GCDH) gene." (PMID 34434904, 2021). "Glutaric aciduria type 1 (GA1, OMIM #231670) is an autosomal recessive disorder of lysine, hydroxylysine, and tryptophan caused by deficiency of glutaryl-CoA dehydrogenase (GCDH, EC 1.3.8.6) enzyme." (PMID 27672653, 2016). "The inherited neurodegenerative disorder glutaric aciduria type 1 (GA1, OMIM 231670) is caused by mutations in the gene for the mitochondrial matrix enzyme glutaryl-CoA dehydrogenase (GCDH, E.C. 1.3.99.7)." (PMID 24498361, 2014).
melanoma (7 papers, 2023 to 2025). A malignant, usually aggressive tumor composed of atypical, neoplastic melanocytes. "In melanoma cells, the loss of GCDH triggers cell death programs that can be prevented by inhibiting DHTKD1." (PMID 40896397, 2025). "GCDH is critical for melanoma cell survival and proliferation through the regulation of metabolic and apoptotic pathways." (PMID 39744494, 2025). "CHAC1 plays a significant role in mediating cell death in melanoma by acting downstream of GCDH (glutaryl-CoA dehydrogenase) inhibition." (PMID 39534397, 2024). "When GCDH is knocked down in melanoma cells, it leads to increased glutarylation of NRF2, a transcription factor that becomes stabilized and transcriptionally active." (PMID 39534397, 2024). "Lower levels of the mitochondrial protein GCDH result in Kglu of the TF NRF2, leading to cell death, indicating that GCDH pathway inhibition is a potential therapeutic strategy for melanoma treatment." (PMID 37143582, 2023). "Consequently, CHAC1 acts as a critical mediator in the apoptosis pathway triggered by metabolic stress due to GCDH inhibition, highlighting its importance in the potential therapeutic targeting of melanoma." (PMID 39534397, 2024). "Moreover, knockdown of GCDH in melanoma cells led to the activation of cell death programs, which could be prevented by inhibiting the upstream lysine catabolism enzyme DHTKD1." (PMID 40896397, 2025). "The knockdown of glutaryl-CoA dehydrogenase (GCDH) results in Nrf2 upregulation and promotes cancer cell apoptosis in melanoma." (PMID 37371607, 2023).
glutaric aciduria (6 papers, 2017 to 2025). "First described in 1975, glutaric aciduria (GA1) is an autosomal-recessive organic acidaemia due to deficiency of glutaryl-CoA dehydrogenase (GCDH) which results in abnormal metabolism of lysine, hydroxylysine and tryptophan." (PMID 40025312, 2025). "Deficiency in glutaryl‐CoA dehydrogenase (GcdH) for glutarate catabolism induces the inherited metabolic disorder glutaric aciduria." (PMID 40832802, 2025). "Mutations in the glutaryl-CoA dehydrogenase (GCDH) gene have also been related to glutaric aciduria, but to type I in this case." (PMID 30872673, 2019). "Glutaric aciduria type 1 (GA1) develops due to mutations in glutaryl-CoA dehydrogenase (GCDH), which results in severe neurologic defects, while glutaric aciduria type 2 (GA2) is caused by mutation of genes involved in electron transfer in the mitochondrial respiratory chain." (PMID 31722069, 2020).
Dystonia (4 papers, 2020 to 2025). An abnormally increased muscular tone that causes fixed abnormal postures. "A dystonia genetic panel showed compound heterozygosity with a pathogenic variant and a variant of uncertain significance in the GCDH gene." (PMID 33728242, 2020). "An identical pattern of combined putaminal and pallidal hypometabolism was seen in two genetic subcategories (THAP1 and GCDH/GA-1); these conditions manifest with dystonia distinguishable on clinical grounds but are often treatment-resistant." (PMID 36445406, 2023).
hepatocellular carcinoma (3 papers, 2024 to 2025). A malignant tumor that arises from hepatocytes. "Recently, it has been demonstrated that GCDH can inhibit the development, progression and metastasis of hepatocellular carcinoma (HCC)." (PMID 39606030, 2024). "GCDH is a mitochondrial enzyme that participates in the breakdown of tryptophan, lysine, and hydroxylysine; its depletion promotes the growth and metastasis of hepatocellular carcinoma, while its overexpression reverses these processes." (PMID 40620061, 2025).
arthrosis (2 papers, 2024 to 2025). "Mediating effect of flavin adenine dinucleotide on the risk of GCDH-osteoarthritis (OA)." (PMID 41567337, 2025). "Finally, identifying specific crotonylation targets in osteoarthritis and elucidating the precise molecular mechanisms by which GCDH regulates FAD biogenesis and signaling are crucial for understanding the downstream mediators of this pathway." (PMID 41567337, 2025).
diabetes (2 papers, 2024 to 2025). "Interestingly, the level of 2‐aminoadipic acid (2‐AAA), a biomarker of diabetes, is significantly increased due to decreased glutaryl‐CoA dehydrogenase (GCDH) expression in CBP/p300‐deficient livers." (PMID 40791184, 2025).
Obesity (2 papers, 2024 to 2026). Accumulation of substantial excess body fat. "Proteins involved in energy metabolism, such as AK2, ADH1B, ACADS, and GCDH, were downregulated in patients with obesity, suggesting impaired lipid metabolism and mitochondrial dysfunction." (PMID 41077621, 2026). "In the present study, we have identified four differentially expressed genes shared between obesity and HCC, namely ESR1, GCDH, FAHD2A, and DCXR." (PMID 38977823, 2024). "Four differentially expressed genes, including ESR1, GCDH, FAHD2A, and DCXR, were found to overlap between HCC and obesity." (PMID 38977823, 2024). "Four differentially expressed genes (ESR1, GCDH, FAHD2A, DCXR) were common in obesity and HCC." (PMID 38977823, 2024).
SCAD) deficiency (2 papers, 2016 to 2018). "In addition, mutations in ACADS gene were detected in four cases of short-chain acyl-CoA dehydrogenase deficiency, and two of them were accompanied with glutaric acidemia (type I or type II ) carried mutations in the GCDH and ETFDH genes, respectively." (PMID 29731766, 2018).
breast carcinoma (1 paper, 2026). "Results showed that four acyl-CoA synthetases—GCDH, ACSS2, ACOX1, and ACOX3—were significantly down-regulated in breast cancer cells, with ACSS2 showing the most pronounced reduction." (PMID 41544165, 2026).
cholera (1 paper, 2023). "Selective pressure for heterozygous carriers of GCDH variants (as described in carriers of cystic fibrosis who have a selective advantage against cholera and other diarrheal disease) is rather unlikely in GA-1." (PMID 38137040, 2023).
chronic kidney disease (1 paper, 2023). Impairment of the renal function secondary to chronic kidney damage persisting for three or more months. "With growing evidence of associations between patient clinical outcomes, namely chronic kidney disease and white matter abnormalities, and the biochemical phenotype, improving GCDH activity could impact patient quality of life." (PMID 37685964, 2023).
deficiencies (1 paper, 2014). "Increased urinary glutaric acid occurs in a variety of neuronal deficiencies such as glutaryl-CoA dehydrogenase (GCDH) deficiency." (PMID 25380056, 2014).